PLXND1 (plexin D1)
Diseases named in the same sentence as PLXND1 in open-access papers (continued):
Sharing a sentence is not in itself a finding about the gene and the disease.
ovarian endometrioid carcinoma (2 papers, 2011 to 2015). "Sema3E/Plexin D1 promotes increased migratory and invasive potential and metastatic growth of ovarian endometrioid carcinoma cells." (PMID 26356073, 2015). "Taken together, our data provide evidence suggesting that PI3K and ERK/MAPK signaling pathways are involved in Sema3E/Plexin-D1-mediated EMT in ovarian endometrioid carcinomas." (PMID 21559368, 2011). "Based on preliminary immuno-screening results, we investigated in detail the expression of Sema3E and its receptors, Plexin-D1 and Neuropilin-1 (Npn1), in human ovarian endometrioid carcinomas." (PMID 21559368, 2011). "Consistent with this idea, we show that the cellular EMT induced by Sema3E/Plexin-D1 in ovarian endometrioid carcinoma cells occurs at least partially through PI3K and ERK/MAPK mediated nuclear translocation of Snail1." (PMID 21559368, 2011). "Collectively, these studies indicate that Sema3E/Plexin-D1 signaling in ovarian endometrioid cancer cells could regulate Snail1 translocation to the nucleus in order to induce EMT and concomitantly augment cell motility." (PMID 21559368, 2011). "Furthermore, Sema3E/Plexin D1 induces EMT through nuclear localization of Snail and PI3K and ERK/MAPK signaling pathways, which play an important role in the Sema3E/Plexin D1-mediated EMT process in ovarian endometrioid carcinoma cells." (PMID 26356073, 2015).
Poland syndrome (2 papers, 2022 to 2025). Poland syndrome is marked by a unilateral absence or hypoplasia of the pectoralis major muscle (most frequently involving the sternocostal portion), and a variable degree of ipsilateral hand anomalies, including symbrachydactyly. "On this occasion, the larger study cohort of MBS yielded 3 de novo PLXND1 gene mutations and 3 additional de novo mutations in the gene REV3L one of whom exhibited incidental features of Poland’s syndrome." (PMID 36581828, 2022).
adenoma (1 paper, 2017). A neoplasm arising from the epithelium. "Analysis of microdissected dysplastic epithelium also revealed possible roles for cancer-related genes not previously associated with CRC (GBP6, PLXND1) in early stage adenoma progression." (PMID 28747659, 2017).
airway hyperresponsiveness (1 paper, 2024). "In this study, we found that deficiency of PLXND1 in CD11c+ DC exacerbates airway hyperresponsiveness (AHR), enhances mucus production, and upregulates collagen gene expression." (PMID 39213301, 2024). "We demonstrated that the lack of PLXND1 in CD11c+ DC exacerbates airway hyperresponsiveness (AHR) parameters, such as airway resistance and tissue elastance." (PMID 39213301, 2024).
brain infarction (1 paper, 2022). Tissue necrosis in any area of the brain, including the cerebral hemispheres, the cerebellum, and the brain stem. "In this study, using a mouse model of transient brain infarction, we aimed to investigate whether Sema3E-Plexin-D1 signaling was involved in cerebrovascular remodeling after ischemic injury." (PMID 33978913, 2022).
brain tumors (1 paper, 2009). "Plexin D1 is expressed on both tumor-associated endothelium and malignant cells in a number of clinical brain tumors." (PMID 19703316, 2009). "We previously demonstrated that PLXND1 is also specifically expressed on vascular endothelium during tumor-associated angiogenesis in a mouse xenograft model of cerebral melanoma metastasis and in a number of human brain tumors, both of primary and metastatic origin." (PMID 19703316, 2009).
cervical cancer (1 paper, 2023). A primary or metastatic malignant neoplasm involving the cervix. "Plexin-D1 may serve as a potential biomarker for cervical cancer, as it was found that it is strongly expressed in the endothelial cells of the cervical cancer samples, and there is no expression of plexin-D1 in endothelial cells derived from normal cervical tissues." (PMID 37627074, 2023).
cervical squamous cell carcinoma (1 paper, 2009). A squamous cell carcinoma arising from the cervical epithelium. "Vascular and tumor cell-associated PLXND1 expression was absent in 3 out of 5 medullary breast carcinomas, one out of 5 cervical squamous cell carcinomas, and all examined vulvar squamous cell carcinomas." (PMID 19703316, 2009).
Glucose intolerance (1 paper, 2019). Glucose intolerance (GI) can be defined as dysglycemia that comprises both prediabetes and diabetes. "Our previous study revealed that Plexin D1 was expressed by inflammatory macrophages and was involved in systemic glucose intolerance." (PMID 30846754, 2019).
hepatocellular carcinoma (1 paper, 2020). A malignant tumor that arises from hepatocytes. "We found that PLXND1 expression in HCC tissues was significantly higher compared with normal liver tissue from Gene Expression Profiling Interactive Analysis (GEPIA) and Integrative Molecular Database of Hepatocellular Carcinoma (HCCDB) databases." (PMID 33489909, 2020).
Insulin resistance (1 paper, 2022). Increased resistance towards insulin, that is, diminished effectiveness of insulin in reducing blood glucose levels. "The Sema3E–Plexin-D1 signaling axis promotes inflammatory macrophage infiltration into visceral white adipose tissues, leading to adipose tissue inflammation and insulin resistance." (PMID 35045890, 2022). "The soluble form of Plexin-D1, which binds to Sema3E and inhibits its activity, markedly suppresses inflammation in adipose tissues and improves insulin resistance." (PMID 35045890, 2022).
ischemia (1 paper, 2022). A hypoperfusion of the BLOOD through an organ or tissue caused by a PATHOLOGIC CONSTRICTION or obstruction of its BLOOD VESSELS, or an absence of BLOOD CIRCULATION. "Moreover, Sema3E-Plexin-D1 signaling is associated with ischemia-induced angiogenesis in the periphery tissue and retina, but its activity in the central nervous system has not been elucidated." (PMID 33978913, 2022). "We found that after ischemia, neurons in the peri-infarct region upregulate Sema3E, and vessels close to the damaged region subsequently express Plexin-D1." (PMID 33978913, 2022). "Dll4 expression was upregulated in Plxnd1iECKO mice, which demonstrated that the absence of Plexin-D1 causes aberrant activation of VEGF signaling in vessel remodeling post-ischemia." (PMID 33978913, 2022). "Therefore, we speculated that Plexin-D1 expression is essential in critical situations, such as vascular remodeling induced by ischemia, where newly sprouting vessels require vascular guidance in response to VEGF signaling." (PMID 33978913, 2022).
leukemia (1 paper, 2019). A malignant (clonal) hematologic disorder, involving hematopoietic stem cells and characterized by the presence of primitive or atypical myeloid or lymphoid cells in the bone marrow and the blood. "Conversely, the PLXND1, PLCB4, HOXA9, HOXA10, TLX3, and NKX2‐1 genes had higher expression in the CIMP+ subgroup, compared to the normal T cells and CIMP− leukemias." (PMID 30575306, 2019).
liver cancer (1 paper, 2020). An epithelial or non-epithelial malignant neoplasm that arises from the liver. "For liver cancer, neither abnormal PLXND1 expression nor its association with clinicopathological parameters of HCC has been reported." (PMID 33489909, 2020). "Prior research on PLXND1 in cancer is limited to cancer types apart from liver cancer." (PMID 33489909, 2020). "For liver cancer, neither abnormal PLXND1 expression nor its correlation with the clinicopathological parameters of HCC have been reported." (PMID 33489909, 2020).
liver cirrhosis (1 paper, 2020). "In addition, univariate analysis revealed the following features as prognostic factors related with both OS and RFS: the expression of PLXND1 and TGF-β1, stage, TH, liver cirrhosis, tumor size, tumor number, and satellite nodules." (PMID 33489909, 2020).
medullary breast carcinoma (1 paper, 2009). An infiltrating breast carcinoma with a relatively favorable prognosis. "Despite its abundant expression in many different tumor types PLXND1 was not expressed on tumor cells and vessels in a subset of medullary breast carcinomas." (PMID 19703316, 2009).
Parkinson disease (1 paper, 2025). A progressive degenerative disorder of the central nervous system characterized by loss of dopamine producing neurons in the substantia nigra and the presence of Lewy bodies in the substantia nigra and locus coeruleus. "In this study, we identified seven hub genes—PI3, TMSB15A, CLEC4M, CD4, SEMA6A, PLXND1, and AVP—that collectively drive Parkinson’s disease progression through synergistic mechanisms." (PMID 41329689, 2025).
pheochromocytoma-paraganglioma (1 paper, 2020). A rare neuroendocrine tumor arising from chromaffin cells of the adrenal medulla (pheochromocytoma) or from sympathetic and parasympathetic ganglia (paraganglioma). "In pheochromocytoma & paraganglioma (PCPG), PLXND1 was negatively, while PLXNB1 and B3 were positively correlated with both RNAss and DNAss." (PMID 32640719, 2020).
renal agenesis (1 paper, 2016). Renal agenesis (RA) is a form of renal tract malformation characterized by the complete absence of development of one or both kidneys (unilateral RA or bilateral RA respectively), accompanied by absent ureter(s). "We also observed kidney phenotypes comprising bilateral and unilateral renal agenesis and/or hypoplasia (Frem2 and 1G, Plxnd1)." (PMID 27002738, 2016).
scoliosis (1 paper, 2015). A congenital or acquired spinal deformity characterized by lateral curvature of the spine. "In addition, the vertebral defects in Plxnd1 mutant mice are reminiscent of the scoliosis in patient P1, and the haemorrhages seen in Plxnd1 mutant mouse resemble the facial haemangiomas seen in patient P1." (PMID 26068067, 2015).
situs inversus (1 paper, 2020). A congenital condition in which there is complete right-to-left reversal of the position of the major thoracic and abdominal organs (that is, they are arranged in a mirror image of the normal positioning). "The same subject SI09 also had a heterozygous mutation in PLXND1 [MIM:604282], a gene which appears among search results for the phenotype ‘situs inversus’ within the Mouse Genome Database57." (PMID 32111882, 2020). "However, while PLXND1 is annotated as a cause of aortic arch and atrial abnormalities in this database, it is not annotated with situs inversus or heterotaxia, so that the basis for the search result is unclear." (PMID 32111882, 2020).
Stroke (1 paper, 2022). Sudden impairment of blood flow to a part of the brain due to occlusion or rupture of an artery to the brain. "Collectively, future studies should explore the involvement of Sema3E/Plexin-D1 signaling in the pericyte coverage process during vascular remodeling after stroke." (PMID 33978913, 2022). "VEGF/VEGFR2 signaling is a master regulatory pathway for vascular development and function in health and disease; therefore, we assumed that Sema3E-Plexin-D1 controlled VEGF signaling after stroke." (PMID 33978913, 2022). "To investigate whether reactivation of Sema3E/Plexin-D1 signaling following stroke leads to vascular alterations, we first monitored CBF in the ischemic region using laser Doppler imaging." (PMID 33978913, 2022). "Therefore, enhancing Sema3E-Plexin-D1 signaling in angiogenic vessels during the critical period of vascular repair could become a new target for stroke treatment." (PMID 33978913, 2022).
type 2 diabetes mellitus (1 paper, 2024). A type of diabetes mellitus that is characterized by insulin resistance or desensitization and increased blood glucose levels. "Recent research, for instance, has uncovered a mechanism of PLXND1, a gene linked in population genetics studies to variations in the distribution of fat between the hips and waists in humans and an elevated risk for type 2 diabetes mellitus (T2DM)." (PMID 38540306, 2024).
vascular malformation (1 paper, 2022). A non-neoplastic disorder that is the result of defects of vascular morphogenesis. "Plexin-D1 deficiency may cause excessively active VEGF signaling and induce functional and structural vascular malformations." (PMID 33978913, 2022).
tumor (41 papers, 2008 to 2025). "In PDAC, SEMA3D and its receptor plexin D1 (PLXND1) have been implicated in tumor invasion and nerve infiltration." (PMID 40981722, 2025). "In contrast to full-length sema3E, p61-Sema3E induces the association of plexin-D1 with ErbB2 and the phosphorylation of ErbB2 and, as a result, induced tumor cell metastasis." (PMID 37627074, 2023). "In cancer plexins can be either oncogenic or tumor suppressors; for example, plexins A1-4 are tumor suppressors while plexin-B2 is tumor promoting and plexin D1 has been associated with tumor vasculature." (PMID 32117864, 2020). "The presence of tumor also induced upregulation of Sema3d, which encodes the ligand for plexin D1 and is involved in angiogenesis, in adjacent normal ECs." (PMID 32440964, 2020). "This is consistent with our results, which showed a relatively high loading of KDR on the principal component associated with VEGFC, NRP1, and PLXND1, which had the second highest association with triple-negative (TN) status in the all-tumor data set." (PMID 23667446, 2013). "In previous work we showed that PLXND1 is expressed in endothelial cells during developmental and tumor-associated angiogenesis." (PMID 19703316, 2009). "In addition, PLXND1 immunoreactivity was also found to be significantly associated with stage, histology grade, TH, tumor number, and satellite nodules, suggesting the potential oncogenic activity of PLXND1 in HCC." (PMID 33489909, 2020). "PLXND1, a key target in tumor-associated endothelial cells, is elevated in these cells but shows reduced expression in patients with pCR, suggesting a potential prognostic role; however, paradoxically, it may also indicate the reduced efficacy of PLXND1--targeted therapy in the pCR group." (PMID 41259828, 2025). "GSEA also revealed a downregulated “Hallmark Androgen Response” gene set and a strong correlation of genes differentially expressed in human NEPC in PLXND1-high relative to PLXND1-low PCa patient tumor samples from both TCGA and SU2C/PCF 2019 cohorts." (PMID 39748059, 2025). "Reducing SEMA3D or its receptor plexin D1 expression inhibits the invasion of tumor cells towards the nerves and decreases the nerve density in tumor tissues." (PMID 37610689, 2024). "Plexin-D1 is expressed aberrantly in many types of solid tumors in both tumor vessels and tumor cells." (PMID 37627074, 2023). "Plexin-D1 mediates inhibitory signals induced by full-length sema3E to inhibit tumor angiogenesis and tumor metastasis." (PMID 37627074, 2023). "SEMA3E is known to act as a repulsive factor for endothelial cells that express plexin-D1, resulting in decreased neoangiogenesis and reduced tumor growth." (PMID 36068209, 2022). "It is supported in another study that tumor cells expressing Sema3D can travel toward PlxnD1-expressing neurons, according to their Diagnosis Related Groups (DRG) in vitro data." (PMID 36713527, 2022). "Sema3E acts as a repulsive factor for plexin-D1-expressing endothelial cells, leading to decreased neoangiogenesis and reduced tumor growth." (PMID 36068209, 2022). "elucidated one mechanism of PDA metastasis formation: Sema3D can bind to PlxnD1 on the surface of PDA tumor cells in the extracellular space by the regulation of its autocrine function control of AnxA2." (PMID 36713527, 2022). "Angiogenesis can also be increased in the presence of semaphorins, and receptors for semaphorin 3C, particularly plexin D1, are upregulated in the tumor vasculature making it a potential drug candidate." (PMID 34270956, 2021). "Emerging data have shown that the expression of PLXND1 is often dysregulated in several types of cancer and acts either as a tumor suppressor or an oncogene." (PMID 33489909, 2020). "TGF-β1, a multifunctional cytokine involved in tumor invasion and progression, displayed the greatest correlations with PLXND1 expression in HCC (Spearman: r = 0.62, P < 2.2e−16)." (PMID 33489909, 2020).
tumor (continued). "Taken together, these findings provide a critical understanding of PLXND1 deregulation in HCC and reveal that PLXND1 likely displays an important role in the tumor immune microenvironment." (PMID 33489909, 2020). "In TISIDB, we found that PLXND1 expression was correlated with several tumor-infiltrating lymphocytes (TILs) in HCC patients." (PMID 33489909, 2020). "Taken together, these results highlight the critical roles of PLXND1 in tumorigenesis, the tumor immune microenvironment, and clinical opportunities for cancer research." (PMID 33489909, 2020). "On the other hand, the PLXND1 gene is involved in body fat distribution and is abundantly expressed in tumor vasculature." (PMID 31766385, 2019). "It controls the interaction between Sema3D and its receptor plexin D1 (PlxnD1) on the tumor cell surface, thereby promoting tumor invasion and metastasis." (PMID 29290958, 2017). "The role in angiogenesis and uniqueness of Plexin D1 expression was explored in tumor cells and vasculogenesis." (PMID 22481931, 2012). "RNAi-mediated knockdown of Sema3E, Plexin-D1 or Snail1 in Sema3E-expressing tumor cells resulted in compromised cell motility, concurrent reversion of EMT and diminished nuclear localization of Snail1." (PMID 21559368, 2011). "Sema3E binds directly with Plexin-D1 to transduce intracellular signal during embryonic or tumor angiogenesis." (PMID 21559368, 2011). "We report here that Sema3E from tumor cells can act on themselves through Plexin-D1 to induce EMT and concomitantly facilitate cell migration and malignant progression." (PMID 21559368, 2011). "Plexin D1 is abundantly expressed on both activated established tumor vasculature and malignant cells in the majority of primary and metastatic clinical tumors, as well as on macrophages and fibroblasts." (PMID 19703316, 2009). "This expression profile highlights Plexin D1 as a potentially valuable therapeutic target in clinical solid tumors, enabling simultaneous targeting of different tumor compartments." (PMID 19703316, 2009). "Whereas a role of PLXND1 in vessel patterning during development is well established, the functional consequences of PLXND1 expression on tumor cells and vessels are less clear." (PMID 19703316, 2009). "We examined Plexin D1 expression in clinical solid tumors (n = 77) of different origin, a selection of pre-malignant lesions (n = 29) and a variety of non-tumor related tissues (n = 52) by immunohistochemistry." (PMID 19703316, 2009). "We demonstrated that PlexinD1 is transcriptionally suppressed by AR via direct AR interaction with PLXND1 promoter, which is a likely mechanism for the upregulation of PlexinD1 observed in PCa tumor clinical samples post-hormone therapy as well as in AR-negative CRPC and NEPC cells." (PMID 39748059, 2025). "SEMA3C has been observed to function as a potent inhibitor of angiogenesis and lymphangiogenesis, which is likely mediated by the activation of plexin-D1-dependent signal transduction in endothelial cells and lymphatic endothelial cells, resulting in the inhibition of tumor progression." (PMID 38505621, 2024). "PLXND1 was initially studied as a tumor promoter and suppressor, but could also play a regulatory role in the development of cardiovascular disease." (PMID 36465455, 2022). "PLXND1 can also act as both a tumour promoter and a tumour suppressor." (PMID 33837646, 2021). "Conversely, as an oncogene, PLXND1 could promote tumor development and progression by aiding in tumor metastasis and epithelial mesenchymal transition (EMT)." (PMID 33489909, 2020). "In addition, PLXND1 was found to be highly correlated with tumor hemorrhage (TH) in this study and plays a critical role in the tumor immune microenvironment." (PMID 33489909, 2020). "Moreover, TISIDB and GEPIA databases were used to investigate the roles of PLXND1 in tumor-immune system interactions in HCC." (PMID 33489909, 2020).